CCL2 (C-C motif chemokine ligand 2)
Diseases named in the same sentence as CCL2 in open-access papers (continued):
Sharing a sentence is not in itself a finding about the gene and the disease.
tumor (continued). "Sarcomas growing in Ptx3−/− host showed a much higher macrophage and neutrophil infiltrate, and higher levels of CCL2, CXCL2, TNFα, IL-6, IL-1β, and VEGF, suggesting an exacerbated tumor-associated inflammatory response." (PMID 26075183, 2015). "Our data suggest that a gradient of CCL2 attracts monocytes/macrophages towards the metastatic tumor microenvironment where they are exposed to high levels of CCL2 and are prompted to secrete another chemokine CCL3." (PMID 26275794, 2015). "There is a growing body of research studies suggest that CCL2 can promote PCa cell proliferation, survival, migration and metastasis, as well as tumor angiogenesis." (PMID 25749044, 2015). "Co-culturing in vitro differentiated adipocytes with tumor cells or with tumor cells and macrophages resulted in similar levels of CCL2 production to the ones expressed by E0771 cells." (PMID 25599228, 2015). "The main findings from our studies are that tumour-derived CatS can transcriptionally regulate the pro-inflammatory chemokine CCL2, in a CD74-dependent manner and influence the tumour microenvironment, by altering cellular recruitment of macrophages." (PMID 26358505, 2015). "It was, for example, demonstrated a few years ago that tumor-entrained neutrophils (TENs), upon stimulation by tumor-derived G-CSF and CCL2, prevent lung metastasis." (PMID 26770016, 2015). "Gene expression of the pro-inflammatory cytokines TNF-α and CCL2 in the tumor were increased in CC compared to WSC, p = 0.020 and p = 0.0354, respectively." (PMID 26732354, 2015). "Macrophage recruitment is stimulated by hypoxia and infiltration into hypoxic tumor areas is guided by tumor-derived factors such as VEGF or CCL2." (PMID 26770016, 2015). "CCL2, CCL22, TGF-β and IL-10 augment the differentiation of M2-like tumor-associated macrophages (TAMs) and recruitment of immunosuppressors including TAMs, MDSCs and Tregs." (PMID 26683520, 2015). "In breast cancer, CCR2/CCL2 interaction recruits macrophages into the lung, where the cells “create” an appropriate microenvironment to facilitate tumor cell lodging and the development of metastatic foci." (PMID 25110692, 2014). "Mast cell activation by complement C5a will cause CCL2 and CCL5 upregulation, which has been to shown to induce Tumor Associated Macrophages (TAMs) to release IL-10, promote angiogenesis, and stimulate tumor metastasis." (PMID 24949488, 2014). "Alternatively, VEGF-A expression can be induced by tumor-released CSF-1 (M-CSF), which acts through NF-κ B activation and, in combination with CCL2, promotes pro-angiogenic functions of macrophages." (PMID 24634660, 2014). "Both proteins, IL-1α and -β, have been implicated in tumor progression by inducing the expression of angiogenic and metastatic genes, cytokines and growth factors, such as MMPs, VEGF, IL-6 and 8, CCl2, CCL7, TNFα and TGFβ." (PMID 24887580, 2014). "Levels of IGF-I, CXCL1, IL-6, and CCL2 were higher in BALF from tumor-bearing mice than naïve mice 32 weeks after urethane treatment, but VEGF levels were unchanged." (PMID 25505466, 2014). "Tumor-derived CCL2 acts as a potent factor for Th2 polarization and shifts monocytes toward the M2-polarized macrophages." (PMID 25125485, 2014). "In a mouse model, BRAFV600E induced expression of CCL2, an immunosuppressive chemokine, while PLX4720 treatment downregulated tumor CCL2 gene expression and increased numbers of CD8 TILs." (PMID 24743024, 2014). "This cluster included the highly angiogenic, malignancy-promoting chemokine CXCL8, as well as the tumor-promoting chemokine CCL2." (PMID 24598028, 2014). "Control and drug-treated cells released CCL2 in the medium, suggesting that chemokines released by the tumor in the microenvironment can influence response to treatment." (PMID 24980831, 2014).
tumor (continued). "M-CSF, together with other tumor-derived factors such as CCL2, induces monocyte infiltration in tumors and macrophage activation toward a trophic pro-angiogenic phenotype (leading to what is called the angiogenic switch)." (PMID 24723924, 2014). "Expressed by macrophages, fibroblasts, endothelial, and tumor cells, CCL2 is one of the most frequently observed chemokines in a wide range of tumors and one of the main determinants of monocyte/macrophage recruitment." (PMID 24723924, 2014). "M2 TAMs support tumor progression through the release of immunosuppressive (i.e., CCL2 and IL-10), proangiogenic (i.e., IL-8 and VEGF), and tissue remodeling (i.e., MMP-2 and MMP-9) factors." (PMID 25136593, 2014). "When investigating the effect of the combination on the tumor inflammatory microenvironment, we found that levels of chemokines including CCL2 were significantly down-regulated in the primary tumors after the combined treatment compared to controls." (PMID 24980831, 2014). "Th17 cells stimulate tumor residential cells to produce CCL2 and CCL20, which provokes the recruitment of dendritic cell, granulocyte, CD4+ T cell, CD8+ T cell, and NK cell to the tumor site." (PMID 24872958, 2014). "For instance, systemic administration of CCL2-neutralizing antibodies in tumor-bearing mice or the short-hairpin RNA knockdown of CCR2 in the cancer cell lines significantly reduced tumor growth along with reduced TAM recruitment." (PMID 25125485, 2014). "CCL2-mediated monocyte recruitment to the tumor is also important in patients suffering from follicular lymphoma." (PMID 24723924, 2014). "Mounting evidence indicates that NF-κB also functions as a regulator of angiogenesis promoting tumor growth by upregulating the expression of angiogenic factors, such as IL-8, CCL2 and VEGF." (PMID 24489934, 2014). "In RCC, however, CCL2 was shown to be of minor importance in the recruitment of macrophages that preserve diverse tumor-promoting functions." (PMID 25193015, 2014). "The available evidence supports that CCL2, a chemotactic factor for monocytes and T lymphocytes plays key roles in tumorigenesis promotion in different tumor types." (PMID 24980831, 2014). "Mast cells infiltration is occurred in the tumor microenvironment in a number of human malignancies in response to tumor-derived chemoattractants such as CCL2 and CCL5." (PMID 24455486, 2014). "Such tumor infiltrating monocytes/macrophages are recruited by CCL2 produced by L-MSCs and CCR2 expressed on TAMs." (PMID 25110692, 2014). "We performed a protein array on tumor explant supernatants and found a significant decrease of monocyte chemotactic protein (1 MCP1) (CCL2), IL6, and tissue inhibitor of metalloproteinase (1 TIMP1) expression in cells expressing DNIIR." (PMID 25280532, 2014). "CCL2 has been correlated with higher tumor grade and has been shown to have significant prognostic value for relapse-free survival." (PMID 24591761, 2014). "Monocytes are recruited by CCL2 to pulmonary metastatic sites of murine breast cancer and promote the extravasation of tumor cells, a necessary step for metastasis, in a process that requires monocyte-derived VEGF." (PMID 24966464, 2014). "This involves upregulated expression of CCR2 and CCL2 by tumor cells that increase the interaction between tumor and vascular ECs." (PMID 25110692, 2014). "Several extrinsic factors previously reported to be associated with the tumor microenvironment were identified, including GCSF, THBS1, S100A8/A9, CCL2, TNF and TNFSF11." (PMID 25593989, 2014). "In fact, in the present study, inhibiting of IL-17A at tumor sites decreased IL-6 and CCL2 in tumors, and the migration of MDSCs in tumor tissues was obviously reduced." (PMID 23372655, 2013). "Consistent with this notion, CCL2 was recently shown to be expressed at the tumor site and attract myeloid suppressor cells that express the CCR2 receptor." (PMID 23533456, 2013).
tumor (continued). "Along these lines, we have identified a predominant mononuclear/macrophage cellular infiltrate in experimental and human MPE, and have shown that these cells are recruited to the malignancy-affected pleura by tumor-derived C-C chemokine ligand 2 (CCL2)." (PMID 23967166, 2013). "Expression of chemokine for monocytes (CSF-1 and CCL-2) were low in tumor cells from EGCG-treated mice, and cytokines of TAM was skewed from M2- into M1-like phenotype by EGCG as evidenced by decreased IL-6 and TGF-β and increased TNF-α." (PMID 24044575, 2013). "TUNEL assay also showed the orthotopic TRAMP-C1 siAR tumours + CCR2atg had the highest number of apoptotic cells, suggesting that both AR and CCL2 pathways are essential signals for PCa tumourigenesis." (PMID 23982944, 2013). "Our results show that CCL2 blockade significantly inhibits tumor growth, and that docetaxel treatment augments this inhibition." (PMID 23698775, 2013). "CCL2 is expressed by endothelial cells within the tumor microenvironment but can also be expressed by tumor cells directly." (PMID 23554889, 2013). "Taken together, our data show that targeting of both tumor and host-secreted CCL2 (or its orthologue, CCL12) in different MPE models yielded similar results, namely inhibition of MPE induction." (PMID 23967166, 2013). "Neutralizing antibodies to CCL2 that blocked CCR2 reduced myeloid suppressor cell migration to the tumor site and reduced MSC-promoted tumor growth." (PMID 23533456, 2013). "We postulated that, in addition to tumor-originated CCL2, chemokine elaborated by host cells contributes to MPE development." (PMID 23967166, 2013). "Our results also show effects of CCL2 blockade on the host response to tumor burden and systemic effects on normal bone." (PMID 23698775, 2013). "CCL2 is known to be a potent chemoattractant for MDSCs, and IL-6 has an impact on survival and proliferation of MDSCs in tumor microenvironment." (PMID 23372655, 2013). "This was shortly followed by the increase of tumor antigen specific CD8 T cells and their migration to tumor sites due to chemokines such as CCL2 and CXCL10 that were released by the activated APCs." (PMID 23555875, 2013). "CCL2 produced by cancer cells recruits MDSCs into tumor and CCL22 produced by M2 macrophages recruits CCR4+ Tregs and Th2 cells into tumor and sentinel lymph nodes." (PMID 23755373, 2013). "We next measured the levels of CSF-1 and CCL-2, major chemokines involved in the monocyte recruitment into tumor microenvironment, in tumor cells isolated from mice by RT-qPCR." (PMID 24044575, 2013). "Among the factors secreted by tumor cells the chemokine CCL2 has been identified as an important priming factor of TAM in vivo." (PMID 23597096, 2013). "For example, myeloid suppressor cells, known to be recruited to tumor sites by CCL2, were recently shown to appear as both monocytes and neutrophils." (PMID 23967166, 2013). "In a different study, over-expression of CCL2 in PC-3 cells increased proliferation and tumor growth in vivo as well as growth of PC-3 cells in the bone after cardiac injection, while inhibition of CCL2 signaling decreased growth of these cells." (PMID 23698775, 2013). "Tumor cells produce colony-stimulating factor-1 (CSF-1) and Chemokine (C-C motif) ligand 2 (CCL2), which are two major attractants and growth factors for TAM." (PMID 24044575, 2013). "In this model, tumor-elaborated CCL2 cannot be neutralized by our murine-specific anti-CCL2 antibodies." (PMID 23967166, 2013). "CCL2 (also called monocyte chemotactic protein-1: MCP-1) is also a well-known potent chemoattractant for monocytes and other immune cells which migrate to areas of inflammation and tumour." (PMID 24216702, 2013). "On the contrary, inhibition of CCL2 and its receptor signaling pathway reduces metastasis in vivo and prolongs the survival of tumor-bearing mice." (PMID 23874655, 2013).
tumor (continued). "Double gene-modified CD3+ T cells successfully demonstrated both CCL2-tropic tumor trafficking and cytocidal reactivity against LK79 cells in vitro and in vivo." (PMID 23441216, 2013). "The selective cytotoxic effect of Yondelis on TAMs significantly reduced their production of IL-6 and CCL2 (a major monocyte chemoattractant recruiting them to tumor tissue)." (PMID 23673510, 2013). "Subcutaneous tumor formation of Col26 increased the serum concentration of CCL2, which was deposited in IVRs and attracted Sirpα+ cDCs therein." (PMID 22815949, 2012). "Immunofluorescence analysis revealed that CCL2 was intensively detected inside the IVRs in the thymus derived from tumor-bearing mice." (PMID 22815949, 2012). "For instance, tumor-derived chemokine CCL2, formerly known as monocyte chemotactic protein (MCP), is critical for the recruitment of macrophages." (PMID 22778768, 2012). "CCL2 is produced by tumor cells, fibroblasts, and macrophages, and high CCL2 levels are correlated with increased numbers of TAMs and a poor prognosis." (PMID 22778768, 2012). "At least some of the recruited cells are known to support tumor growth, such as macrophages (by CCL-2 and CCL-7) and T-regulatory cells (by CCL-17)." (PMID 22348096, 2012). "This assumption is supported by the observation that CCL2 was detected in the IVRs in non-tumor-bearing mice after intravenous injection of recombinant (r) CCL2." (PMID 22815949, 2012). "TAM recruitment in tumours is mediated by several cytokines, of which CCL2 seems to be the main player; other chemokines involved in monocyte recruitment are CCL5, CCL7, CXCL8, and CXCL12, as well as cytokines such as VEGF, PDGF, and the growth factor M-CSF." (PMID 22778767, 2012). "We have also shown that migration is dependent on CCR2 expressed by T cells and CCL2 secreted by tumor cells." (PMID 21450101, 2011). "Beside the effect on monocytes, CCL2 has also been shown to inhibit the generation of tumor-reactive T cells." (PMID 22162712, 2011). "Both excess CCL2 and anti-CCL2 Ab were able to inhibit T cell migration and tumor cell apoptosis significantly (p < 0.05)." (PMID 21450101, 2011). "In those studies, the level of tumor derived-CCL2 and its influence on T cell infiltration of tumor cells is unclear." (PMID 21450101, 2011). "For example, it was believed that neutralizing CCL2 would be of beneficial potential for the control of CCR2-expressing tumor cells." (PMID 21943176, 2011). "We investigated the distribution of CCR2 and CCL2 in T cells and tumor cell lines, respectively, established from specimens of additional CRC patients." (PMID 21450101, 2011). "Expression of CCL2 is correlated with TAM migration to the tumor, with high expression resulting in higher numbers of TAM, as well as a higher growth rate of tumors after in vivo transplantation." (PMID 22162712, 2011). "Inclusion of excess CCL2 in T-cell layer or Ab to CCL2 in separating layer of collagen fibroblasts blocked the migration of CTLs toward tumor cells and in turn significantly inhibited tumor cell apoptosis." (PMID 21450101, 2011). "Second, by inhibiting Akt phosphorylation, rVP1 also attenuates IKK phosphorylation, NF-κB activation, and CCL2 production, thus suppressing tumor migration/invasion and promoting tumor cell death." (PMID 21826248, 2011). "In patients with breast or ovarian cancer, high serum levels of CCL2 positively correlated with tumor development." (PMID 21826248, 2011). "Several cytokines and chemokines are present at high levels in the tumour microenvironment, compared to normal tissues, such as CCL2 (MCP-1), CXCL1 (GROα) and CXCL5 (ENA-78)." (PMID 22125641, 2011). "CCL2 has also been previously reported to induce angiogenesis, which is important for tumour growth and metastasis." (PMID 22125641, 2011). "In HPV16 tumor models, a role for CCL2 in the recruitment of macrophages for the tumor site was described by Pahler and collaborators." (PMID 20525400, 2010).
tumor (continued). "We previously reported that CCL2 is generally expressed in various tumor types of both human and mouse and CCR2 is expressed by MDSCs." (PMID 20111717, 2010). "As a consequence of this central role in the tumor microenvironment, CCL2 is being the object of several studies and is included in the list of potential targets for novel therapies." (PMID 20805891, 2010). "MCP-1/CCL2 recruits TAM to the tumor site, and these cells release IL-6 and contribute to tumor stroma formation and angiogenesis." (PMID 19582164, 2009). "Low level secretion was found to stimulate tumour growth through angiogenesis mediated by monocyte activation, whereas high levels of CCL2 attracted large numbers of monocytes/macrophages and rapid tumour destruction." (PMID 15900302, 2005). "Chemokine (C-C motif) ligand-2 (CCL2) is a chemoattractant and activator of macrophages and is a key determinant of the macrophage infiltrate into tumours." (PMID 15900302, 2005). "This is an important new finding and demonstrates that CCL2 expression is silenced or downregulated in the majority of ovarian cell lines and primary tumours." (PMID 15900302, 2005). "Four tumours expressed CCL2 in 0–5% of epithelial cells, six tumours expressed CCL2 in 6–25% of epithelial cells, while only three tumours expressed CCL2 in greater than 25% of the epithelial cells." (PMID 15900302, 2005). "Analysis of the CCL2 locus at 17q11.2–q12 showed loss of heterozygosity (LOH) in 70% of primary tumours, and this was significantly more common in tumours of advanced stage or grade." (PMID 15900302, 2005). "The level of CCL2/MCP-1 expression is correlated with the increased infiltration of macrophage and the grade of tumour." (PMID 15164120, 2004). "Multi-omics analyses, combined with functional in vitro and in vivo mechanistic studies, revealed that PKD1 modulated the "desert" tumor immune microenvironment via C-C motif chemokine ligand 2 (CCL2), and targeting CCL2 could reverse immunotherapy resistance." (PMID 41766665, 2026). "Once activated, HIF‐1α enhances the secretion of CCL2 from the tumor." (PMID 41160815, 2026). "The CCR2-DC-ANVs target tumour by leveraging the C-C motif chemokine ligand 2 (CCL2) in tumours." (PMID 42209521, 2026). "Our previous findings demonstrated that post-RT CCL2 secretion by specific murine cancer cells, such as MB49 and LLC cells, contributes to the interactions with both tumor associated macrophages (TAMs) and Tregs in the post-irradiated TME, which increases the risk of badscopal effect." (PMID 41486114, 2026). "However, we will focus on CCL2 and GM-CSF in this manuscript and demonstrate their role in tumor microenvironment." (PMID 41513619, 2026). "Moreover, QPCTL shapes the tumor microenvironment by modulating macrophage recruitment and polarization through modification of CCL2." (PMID 41988205, 2026). "Consequently, our findings demonstrated that cancer cells secrete the chemokine C‐C motif ligand 2 (CCL2) as a signaling molecule, which induces lipolysis in neighboring adipose tissue, thereby promoting FA release and tumor growth." (PMID 41160815, 2026). "Specifically, tumor cells induced secretion of CCL2 (C-C motif chemokine ligand 2), leading to macrophage activation and subsequent TWEAK secretion by tumor cells via the CCL5/TRAF6 (TNF receptor-associated factor 6)/NF-κB signaling axis, which stimulated muscular atrophy." (PMID 40427186, 2025). "However, some can also promote tumor growth via recruiting immunosuppression cells, such as MDSCs, especially CCL2." (PMID 39947253, 2025). "Additionally, tumor-secreted TGF-β promotes the paracrine production of CCL2 and CCL17, recruiting N2-polarized neutrophils and establishing an immunosuppressive microenvironment." (PMID 40563367, 2025). "Furthermore, research has found that the deletion of certain Y chromosome genes activates inflammation-related pathways (e.g., IL-6 and CCL2), promoting tumor development." (PMID 40248204, 2025).